PTGS2 (prostaglandin-endoperoxide synthase 2)
Diseases named in the same sentence as PTGS2 in open-access papers (continued):
Sharing a sentence is not in itself a finding about the gene and the disease.
tumor (continued). "Moreover, combination treatment showed downregulation of the expression of inflammation-related genes that are involved in tumor inflammation, such as Gremlin (GREM1), IL-1β, IL-4, NF-κB, and prostaglandin-endoperoxide synthase 2 (PTGS2), tumor nitric oxide level." (PMID 34959865, 2021). "Thus, the expression of PTGS2 at the luminal surface of CRC, in non-tumor cells, did not apparently associate to a M1->M2 switch of macrophages." (PMID 32168749, 2020). "Therefore, similar to IL-1β, PTGS2 will not promote tumor progression through sustained inflammatory stimuli in early-stage LUAD." (PMID 32556504, 2020). "Although ligustrazine and ferulic acid suppressed PTGS2 and MTOR in tumor or nervous system diseases, the cooperation of ligustrazine, ferulic acid, and tetrahydropalmatine is unknown whether or not via PTGS2 or MTOR, in spite of their valid effect in EMS." (PMID 31781263, 2019). "As celecoxib served as PTGS2 inhibitor and inhibited PGE2 formation, administration of celecoxib might attenuate the effects of PGE2 on tumor microenvironment and indirectly suppressed tumor growth in vivo." (PMID 31440159, 2019). "In this study, RYNXC could significantly decrease ESR1, PGR, EGFR, PTGS2, and Src mRNA expressions in a dose-dependent manner in MCF-10AT cells or breast precancerous lesion model rats, which could further inhibit cell proliferation and tumor progression." (PMID 30906412, 2019). "Similarly, IH induced an up-regulation of PTGS2 expression in macrophages (p = 0.003), while no changes were observed in the PTGS2 gene expression in tumor cells." (PMID 28300223, 2017). "Because PTGS2 is not constitutively expressed in tissues but is induced by growth factors, inflammatory cytokines, and tumor promoters, the effect of NSAIDs on PTGS2 may differ by tissues." (PMID 23967159, 2013). "Interestingly, we found that expression of PTGS2 but not PTGS1 was elevated in PTGER4 tumour xenografts compared with WT xenografts." (PMID 21589857, 2011). "However, unlike our observations in tumor cells, the expression of IL-1β, PTGS2, and their receptors was positively regulated by piperine in HaCaT cells, indicating the pro-inflammatory action of non-tumor cells against this molecule, which can be considered a stress stimulus." (PMID 36678600, 2023). "In this study, pBD2 showed anti-tumor potential by upregulating the expression of PTEN and downregulating the expression of SPRY2 and PLAU, and pBD2 was also shown to promote cell proliferation by upregulating the expression of CDC25A, E2F2, and PTGS2, which perhaps might lead to tumorigenesis." (PMID 36077151, 2022). "COX-2, encoded by PTGS2 shares 81% homology with COX-1, is usually absent from healthy tissue and is transiently induced by pro-inflammatory stimuli, growth factors, cytokines, and tumor promoters to increase the rate of prostaglandin formation after tissue injury." (PMID 23388178, 2013). "The comparison of tumor tissue (TU) and adenomatous polyp tissue (TU) highlights that the expression of CXCL1, CXCL8, and PTGS2 does not differ significantly (adj." (PMID 38979413, 2024). "Within the tumor population, we identified expression of phospholipase enzymes PLA2G2A and PLA2G4A and PTGS2 (COX2), but not PTGS1 (COX1)." (PMID 36277993, 2022). "In tumor cells, PGE2 production was also increased in response to IH; however, no changes on PTGS2 gene expression were detected." (PMID 28300223, 2017). "We found elevated expression of PTGS2 (P<0.001) but not PTGS1 in PTGER4 xenograft tumours compared with WT tumours." (PMID 21589857, 2011). "Tumor-derived prostaglandins have previously been reported to prevent the accumulation of CD103+ DCs into the TME; however, we did not observe increased CD103+ DCs in Ptgs2−/− tumors." (PMID 38635884, 2024). "PTGS2/COX2 expression trended lower in aspirin users, but not with tumor response." (PMID 33430037, 2021).
tumor (continued). "Moreover, despite the influence of tumor stroma and leucocyte infiltration in CRC progression, previous studies did not evaluate the influence of PTGS2 expressed by non-tumor cells on patient prognosis." (PMID 32168749, 2020). "Decreased (hydroxyprostaglandin dehydrogenase 15 (15-PGDH, HPGD) mRNA expression in tumor samples relative to that of normal samples was obvious, whereas prostaglandin-endoperoxide synthase 2 (COX-2, PTGS2) mRNA failed to present a difference between tumor and normal samples." (PMID 30531928, 2018).
cancer (747 papers, 2002 to 2026). A tumor composed of atypical neoplastic, often pleomorphic cells that invade other tissues. "Given the central role of PTGS2 in inflammation and the association between inflammation and cancer, it is reasonable to expect that PTGS2 would be overexpressed in cancer." (PMID 40444088, 2025). "Overall, most (but not all) studies suggest an association between the SNP -765 G>C of the PTGS2 gene, particularly the C carrier, and an increased risk of various cancers." (PMID 40184332, 2025). "Inflammation caused by PTGS2 promotes the survival of cancer cells and their resistance to therapy because inflammatory cells can create inflammatory mediators that support cell survival and confer resistance to therapies that cause cell death." (PMID 38426619, 2024). "Several reports have linked the immune system, cancer, and PTGS2, demonstrating that its expression induces Tregs, and these cells support cancer-mediated immune suppression." (PMID 39450252, 2024). "Studies on cancer cells have indicated that ferroptosis can directly increase the expression of PTGS2 and cause inflammation by accelerating AA metabolism and promoting the secretion of pro-inflammatory molecules." (PMID 38413694, 2024). "Elevated PTGS2 transcription is a hallmark of ferroptosis in malignant neoplasms, inflammatory, neurological diseases." (PMID 38483700, 2024). "We also explored the expression of the underlying cancer‐promoting genes within cluster 3; these genes included Cdkn1a, Plaur, Ptgs2, Cox17, Lilrb4q, G0s2, Egr1, and Cxcl2, with previous reports suggesting their implication in increasing cancer progression." (PMID 39113226, 2024). "Levels of IL8 and PTGS2 transcripts were also significantly increased in the cancer group, reinforcing their association with cancer-related inflammation." (PMID 39523395, 2024). "For example, the induction of ferroptosis by erastin (a small molecule implicated in cancer therapy) has been associated with an increased expression of prostaglandin-endoperoxide synthase, which is also known as cyclooxygenase-2 (PTGS2/COX2)." (PMID 36976734, 2023). "Removing an ‘outlier’ from the Ptgs2 dataset (the highest value, 2.05, was > 2 SD from the mean), uncovered 70% reduced Ptgs2 expression in βPix-deficient cancers (0.32 ± 0.08, mean ± SE; p = 0.03)." (PMID 37805544, 2023). "PTGS2 has been implicated in tumorigenesis and recognized as a potential target for the management of cancer." (PMID 35740546, 2022). "The association of PTGS2 with cancer, cardiovascular disease, and multiple diseases has been confirmed in a variety of studies." (PMID 33542744, 2021). "Stromal PTGS2 was prevalently expressed by cancer-associated fibroblasts exerting a barrier function near the gut lumen, and it apparently favored the antitumor M1 macrophage population." (PMID 32168749, 2020). "We linked PTGS2 with NF‐κB signaling pathway, which is closely related to cancer cell proliferation and radio‐tolerance and we find that PTGS2 influenced radiotherapy tolerance of U87 cells through the NF‐κB signaling pathway." (PMID 30740906, 2019). "In this study, we linked PTGS2 with NF‐κB signaling pathway, which is closely related to cancer cell proliferation and radiotherapy tolerance." (PMID 30740906, 2019). "Among the different mediators of inflammation, PTGS2 clearly appear to be implicated in cancer progression, by stimulating cell proliferation, cell invasion, inducing vessel formation, and enhancing metastasis and immunosuppression." (PMID 31920649, 2019). "In this meta-analysis, the researchers had two goals: (a) to determine the relationship between the PTGS2 rs5275 polymorphism and cancer risk and (b) to investigate the effect of NSAID use on preventing cancer." (PMID 29552297, 2018). "Many genes, such as Bcl-xl, kRAS, COX, iNOS, APC, Smad3, STAT3, Ptgs2, Tnfrsf6, p16, Mlh1, Runx3, Dapk, and β-catenin are mutated in stages of carcinogenesis of the UC-associated cancer." (PMID 28621756, 2017).
cancer (continued). "rs2243250 (IL4) and rs5275 (PTGS2) were found to be significantly associated with shorter cancer-specific survival (CSS)." (PMID 28117391, 2017). "The inflammation amplifier reflect genes associated with cancer development, and several genes from the amplifiers were found up-regulated in necrotic tumors, like PTGS2, IL6, SERPINE1 and SOD2." (PMID 26485755, 2015). "For PTGS2, there have been studies of 4 SNPs (rs5275, rs20417, rs689466, and rs2745557), which were analyzed for an association with cancer risk and NSAID use; however, the studies have produced mixed results." (PMID 23967159, 2013). "Second, we only focused on five common polymorphisms, and is encouraged to examine more polymorphisms, especially the low-penetrance polymorphisms from other promising cancer-susceptibility genes, such as PTGS2 and CYP2E1 genes." (PMID 23874853, 2013). "In the past five years, several studies have aimed to evaluate the impact of PTGS2 SNPs on the risk of developing different types of cancer." (PMID 21059239, 2010). "Certain SNPs in PTGS1 and PTGS2 genes have been linked to cancer." (PMID 40184332, 2025). "Interestingly, PTGS2 was not only found to be involved in the metabolic pathway but also demonstrated an association with cancer development." (PMID 40661231, 2025). "Thus, patients’ cancers exhibited high expression levels of PTGS2/ESR2/EGFR/JUN/MMP2 genes’ signatures are associated with poor prognosis." (PMID 39707884, 2024). "PTGS2 is involved in various processes leading to inflammation, and plays a causal role in cancer." (PMID 39560493, 2024). "Furthermore, mutations in microRNA binding sites in the 3'UTR of the PTGS2 gene are significantly associated with cancer risk." (PMID 35341150, 2022). "PTGS2 encodes inducible prostaglandin synthase cyclooxygenase-2, which is an important rate-limiting enzyme produced by prostaglandins and has a key significance for malignant tumors." (PMID 33688358, 2021). "However, the results obtained in the present study are in contrast with results from the Danish prospective Diet, Cancer and Health cohort, where we found that high PTGS2 mRNA level-associated PTGS2 variant alleles were associated with lower risk of CRC." (PMID 25166592, 2014). "In the present study we were unable to detect an altered risk of cancer for carriers of the G-765C variant C-allele, probably due to the strong linkage to T8473C variant C-allele, an allele with the opposite effects on the PTGS2 mRNA level." (PMID 25166592, 2014). "Cases and controls were first compared with regard to the distribution profile of clinical aspects potentially implicated in the risk of developing cancer and that could interfere as confounding factors on the analysis of the risk associated to PTGS2 SNPs." (PMID 21059239, 2010). "Furthermore, it is suggested that genetic variation in PTGS1 and PTGS2 might be related to cancer risk and/or drug efficacy in humans." (PMID 23967159, 2013). "Consistent with mRNA expression, ATF3, HO1, CHAC1, and PTGS2 are significantly up-regulated in cancer cells after challenging with Fe-EGCG@RSL3." (PMID 40530387, 2025). "To understand the role of cancer-cell-derived PGE2 in immune evasion, we ablated PGE2 production through cyclooxygenase-1 (COX1; encoded by Ptgs1) and COX2 (encoded by Ptgs2) KO in RTT cells and engrafted them into Rag2–/– mice." (PMID 39604727, 2025). "While PTGS2 is often overexpressed in cancer and acts in a pro-inflammatory capacity, its expression was significantly reduced in IPAH." (PMID 41137320, 2025). "This putative axis is plausible given the well-established role of NF-κB as a transcriptional activator of PTGS2 in other pathological contexts, such as inflammation and cancer." (PMID 41008977, 2025). "We finally aimed to study the genes implicated in cancer cell migration as a mechanism of rescue, thus we analyzed the expression of ACTN1, PTGS2, and RAC1." (PMID 40032892, 2025).
cancer (continued). "PTGS2 is expressed in many types of cancer and plays a multifaceted role in carcinogenesis or promotion of carcinogenesis and the resistance of cancer cells to chemical and radiation therapies." (PMID 40643495, 2025). "Cyclooxygenases play a central role in inflammatory processes, and the link between cancer and inflammation has prompted investigations about PTGS1 and PTGS2 expression across many cancer types." (PMID 40444088, 2025). "By leveraging RNA sequencing, network pharmacology, molecular docking, and molecular dynamics, this study has elucidated how bioactive metabolites like C3G and ursolic acid interact with key cancer-related proteins, such as PTGS2, HSP90AA1, and ERBB2." (PMID 40141751, 2025). "Saindane and colleagues conducted a multi-omic approach to assess the comprehensive median expression of PTGS2 across 30 cancer types." (PMID 40444088, 2025). "In particular, Guanosine 2',3'-cyclic phosphate demonstrated exceptional binding activity to multiple docked target proteins, exhibiting the strongest binding affinity to PTGS2 (-14.1 kcal/mol), suggesting its potential significance in cancer therapy." (PMID 40877012, 2025). "Palmitoleic acid, geraniol, and tyrosol play crucial roles in anti-inflammatory and anti-cancer processes through their regulation of PTGS2 (Prostaglandin-Endoperoxide Synthase 2)." (PMID 40699728, 2025). "In order to better understand the mechanisms of cancer progression, some mediators (PTGS2 and PTGER4), which have been extensively studied by our research group previously, have been verified." (PMID 38891950, 2024). "Among these, guanylate cyclase, metallothionein, homeobox, olfactory receptor, prostaglandin-endoperoxide synthase 2, matrix metallopeptidase 12, and chrysrallin play roles in different types of pain, including visceral, neuropathic, and cancer-related pain." (PMID 38397842, 2024). "In human PDAC, the presence of ephrin-A receptor 2 (EPHA2) led to the upregulation of prostaglandin endoperoxide synthase 2 (PTGS2) in cancer cells, with a subsequent T cell exclusion from PDAC TME." (PMID 38817612, 2024). "The expression of prostaglandin‐endoperoxide synthase (PTGS2, also known as cyclooxygenase 2) changes during inflammation and cancer initiation." (PMID 38722284, 2024). "Dex-treatment leads to the destabilization of ARE-containing mRNAs of TNF and CXCL8, and PTGS2 in cancer cells." (PMID 38195703, 2024). "Additional markers have been proposed such as PTGS2 (Cyclooxygenase-2) mRNA levels in cancer, or malondialdehyde (MDA) and 4-hydroxynonenal (4-HNE), which are transiently formed from peroxidized lipids but unstable." (PMID 38653992, 2024). "PTGS2 is the primary target of aspirin and impacts cancer survival through six primary pathways: the interleukin pathway, extracellular matrix pathway, signal transduction pathway, apoptosis pathway, autophagy pathway, and DNA repair pathway." (PMID 38201650, 2024). "The chemical inhibition of system Xc- by erastin (a prototype trigger of ferroptosis) also results in PTGS2 upregulation in cancer cells." (PMID 38483700, 2024). "Strikingly, 22 of 31 cancer types (70%) in TCGA datasets showed positive correlations (Pearson coefficient r > 0.3) between Yap1 signature (51-gene core signature) and PTGS2 (Cox2) mRNA expression." (PMID 39468013, 2024). "Next, an online Kaplan-Meier plot was used to assess the predictive value of the PTGS2/ESR2/EGFR/JUN/MMP2 genes’ signature expression level on OS in numerous human cancers." (PMID 39707884, 2024). "Hallmark Kras Signaling UP and Hallmark KRAS Signaling DN (Overlap Genes including PTGS2, IGF2): KRAS signaling is pivotal in many cancers, affecting cell growth, apoptosis, and migration." (PMID 39000413, 2024). "In terms of protein expression, our findings showed that the treatment reduced PTGS2 in both cells studied, indicating that piperine modulates gene and protein expression in our cancer model." (PMID 38891950, 2024).